MTOR (mechanistic target of rapamycin kinase)
Diseases named in the same sentence as MTOR in open-access papers (continued):
Sharing a sentence is not in itself a finding about the gene and the disease.
hyperthyroidism (6 papers, 2012 to 2024). Overactivity of the thyroid gland resulting in overproduction of thyroid hormone and increased metabolic rate. "A Gene Ontology functional enrichment analysis of microarray data comparing SKM from euthyroid and hyperthyroid patients showed that hyperthyroidism negatively associated with mTOR, AMPK, PI3K/Akt, p70S6K and MAPK signaling." (PMID 34675885, 2021). "Secondly, in the context of hyperthyroidism, T3 increases mTOR signaling in the ARC, leading to an increase in food intake." (PMID 31176677, 2019). "In keeping with these data, we have recently reported that thyroid hormone-induced feeding, both short-term (central administration) and long-term (hyperthyroidism), is mediated by selective modulation of the mTOR pathway in the ARC, which elicits increased expression of AgRP and NPY." (PMID 23056530, 2012). "On the other hand, in hyperthyroidism, high levels of T3 increase BCAA oxidation and positively regulate mechanistic target of rapamycin (mTOR), increasing thermogenesis." (PMID 39195533, 2024).
hypophosphatemia (6 papers, 2016 to 2026). Lower than normal levels of phosphates in the circulating blood. "mTOR inhibitors are associated with hypophosphatemia, and monitoring is recommended monthly for mild hypophosphatemia, weekly for moderate hypophosphatemia, and daily for severe hypophosphatemia, with no recommendation for initial phosphate measurement." (PMID 41146174, 2025). "Additional agents that may cause hypophosphatemia include carbonic anhydrase inhibitors, corticosteroids, acetaminophen overdose, antiandrogens, anticonvulsants, antineoplastics, mTOR inhibitors, calcineurin inhibitors, and alcohol." (PMID 40725553, 2025). "Supplementation for mTOR inhibitor-induced hypophosphatemia is recommended when the phosphate level is < 0.81 mmol/L (2.5 mg/dl), with oral administration for mild and moderate hypophosphatemia and intravenous administration for severe hypophosphatemia." (PMID 41146174, 2025).
IgA nephropathy (6 papers, 2019 to 2026). "We present a case of pyomyositis caused by Staphylococcus aureus in a patient with IgA nephropathy and a kidney transplant, under treatment with mTOR inhibitors and prednisone." (PMID 30911428, 2019). "We found that rapamycin can improve renal function and delay the progression of IgA nephropathy as a specific mTOR pathway antagonist." (PMID 31057050, 2019). "This study suggests that mTOR pathway is activated and participates in the development of IgA nephropathy, which means mTOR pathway might be an important target for IgAN treatment." (PMID 31057050, 2019). "At present, some studies revealed that the mTOR pathway may participate in IgA nephropathy; however, the mechanism has not been systematically studied." (PMID 31057050, 2019).
ischemic disease (6 papers, 2016 to 2025). Lack of blood supply to an area of the body, resulting in impairment of tissue oxygenation. "Accumulating evidence suggests that the mTOR/HIF‐1α pathway is associated with ischemic diseases such as ischemic myocardial infarction due to its pro‐angiogenic effect." (PMID 40032632, 2025). "Abnormal mTOR activation is linked to a number of illnesses, including ischemic diseases; BCAAs, particularly leucine, activate the mTOR pathway." (PMID 38034996, 2023). "The inhibitory effect of BBR on BCAAs may therefore play a role in reducing the risk of developing ischemic diseases via mTOR." (PMID 38034996, 2023). "Altogether, these findings support that Akt-mTOR-GSK3β pathway is a key target for therapy in ischemic diseases." (PMID 33614654, 2021). "The role of mTOR signalling pathway in ischemic disease have been suggested recently." (PMID 29921218, 2018). "Several studies documented that mTOR can be the therapeutic target in various ischemic diseases." (PMID 27936094, 2016). "Furthermore, several in vivo and in vitro studies have shown MSC-mediated pleiotropic activity in stimulating angiogenesis in ischemic disease, myelination, dendritic and axonal regeneration through IGF secretion, and mTOR pathway activation." (PMID 33957957, 2021).
kaposiform hemangioendothelioma (6 papers, 2020 to 2025). Kaposiform hemangioendothelioma is a very rare, aggressive, vascular tumor manifesting in the neonatal period or in infancy as cutaneous vascular tumors to large infiltrative lesions. "In contrast to normal lymphatic vessels, endothelial cells of LM, kaposiform lymphangiomatosis and kaposiform hemangioendothelioma expressed mTOR." (PMID 35526176, 2022). "Since the first reports on the successful use of mammalian target of rapamycin (mTOR) inhibition for the treatment of kaposiform hemangioendothelioma (KHE), sirolimus rapidly evolved from a compassionate use agent to an established therapeutic option for this entity." (PMID 35676905, 2022). "Sirolimus, an inhibitor of the mammalian target of rapamycin (mTOR), has been extensively investigated for its therapeutic potential across a range of diseases and has achieved notable prominence in the management of kaposiform hemangioendothelioma (KHE) in recent years." (PMID 40894922, 2025).
Kidney Cyst (6 papers, 2015 to 2025). Abnormal fluid filled sac within the kidney, either acquired or congenital. "Our data reveal that S6K1 hyperactivity alters centrosome positioning in mitotic cells, affecting oriented cell division and promoting kidney cysts in conditions of mTOR hyperactivity." (PMID 32581239, 2020). "Since we have demonstrated that Flcn deficiency leads to the activation of the mTOR pathway in those kidney cysts, we expected that mTOR was also activated in these high-grade allograft RCCs originated from the cystic hyperplasia/micro-tumor cells." (PMID 26418749, 2015). "The mTOR pathway is aberrantly activated in ADPKD kidney cysts." (PMID 38396765, 2024). "Indeed, overactivation of the PI3K/Akt/mTOR pathway was found to encourage hyperproliferation in cancer and kidney cysts." (PMID 36422197, 2022).
malignant peripheral nerve sheath tumor (6 papers, 2017 to 2024). Malignant peripheral nerve sheath tumor (MPNST) is a rare and often aggressive soft tissue sarcoma occurring in a wide range of anatomical sites. "Much of the pharmacologic treatment options for NF1 pain remain in clinical and preclinical stages, including those that target mTOR or MEK pathways for malignant peripheral nerve sheath tumors." (PMID 39239489, 2024). "A possible role for mTOR inhibition in neurofibromatosis type 1-related malignant peripheral nerve sheath tumour (MPNST) has also been postulated." (PMID 28571564, 2017). "c-Maf reduces the anchorage-independent growth and metastasis ability of malignant peripheral nerve sheath tumor (MPNST) through targeting DEPTOR, a negative regulator of the AKT/mTOR pathway." (PMID 36750911, 2023).
megalencephaly-capillary malformation syndrome (6 papers, 2017 to 2023).
non-melanoma skin carcinoma (6 papers, 2015 to 2025). "Compared to other immunosuppressives, mTOR inhibitors and mycophenolate mofetil have been associated with a decreased risk of developing post-transplant non-melanoma skin cancers." (PMID 26239556, 2015). "Although the effects of mTOR among KTx recipients have been shown mostly for non-melanoma skin cancer, future studies evaluating the effects of different immunosuppressive regimens on mortality in KTx patients with RCC are needed." (PMID 30999706, 2019). "Calcineurin inhibitors are associated with a higher neoplastic risk, while mTOR inhibitors, particularly sirolimus, may reduce the risk of HCC recurrence and non-melanoma skin cancer." (PMID 40141766, 2025).
osteonecrosis (6 papers, 2021 to 2025). A none disease characterized by death of bone tissue due to a lack of blood supply. "Subsequently, other drugs, including denosumab and those with antiangiogenic properties—such as tyrosine-kinase inhibitors (TKIs), vascular endothelial growth factor (VEGF) inhibitors, and the mammalian target of rapamycin (mTOR)—have also been linked to the development of osteonecrosis." (PMID 41437101, 2025). "In addition to bone targeting drugs, medications without antiresorptive properties such as angiogenic inhibitors, tyrosine kinase inhibitors or inhibitors of the mammalian target of rapamycin (mTOR) and cytotoxic molecules used for chemotherapy may also increase the risk of osteonecrosis of the jaw." (PMID 33567797, 2021). "Oral lithium reduced the osteonecrosis rates in a rat model of GC‐ONFH, and restrained the increased expression of autophagy related proteins in bone tissues through PI3K/AKT/mTOR signalling pathway." (PMID 38801405, 2024).
Proteus syndrome (6 papers, 2017 to 2025). Proteus syndrome (PS) is a very rare and complex hamartomatous overgrowth disorder characterized by progressive overgrowth of the skeleton, skin, adipose, and central nervous systems. "Proteus syndrome is caused by somatic activating mutations in AKT1, which leads to overactivation of PI3K/AKT/mTOR signaling pathway as PROS-associated PIK3CA mutations." (PMID 34074347, 2021). "Alternative treatment strategies may include AKT inhibitors that have shown promise in the related overgrowth disorder of Proteus Syndrome, dual MTORC1/2 inhibitors that are in development in oncology, or antisense oligonucleotide therapies directed towards MTOR transcripts." (PMID 34197453, 2021).
T-cell leukemia (6 papers, 2011 to 2024). A malignant disease of the T-lymphocytes in the bone marrow, thymus, and/or blood. "“MTOR_UP.N4.V1_DN” signature consists of genes downregulated upon treatment of CEM-C1 T cell leukemia cells with an MTOR inhibitor rapamycin." (PMID 37700842, 2023). "Rapamycin, an inhibitor of mTOR, significantly inhibits CXCL12 mediated migration of both primary human resting T cells and human T cell leukemia cell line CEM." (PMID 21931802, 2011).
testicular cancer (6 papers, 2021 to 2025). A primary or metastatic malignant neoplasm that affects the testis. "Moreover, hyperactivation of phosphatidylinositol 3‐kinase (PI3K)/Akt/mTOR signalling is linked to different forms of cancer including testicular cancer." (PMID 35569037, 2022). "An analysis of co-expression of proteins in the hormonal clusters #1 and #3 of TCGA testicular cancers underline the relevance of EGF/ERBB, MAPK and AKT/mTOR signaling pathways, whose members were identified as prominent hubs of communities of co-regulated proteins." (PMID 40011822, 2025).
thymic carcinoma (6 papers, 2013 to 2023). Thymic carcinoma (TC) is a type of thymic epithelial neoplasm characterized by a high malignant potential. "Patients with advanced/metastatic thymoma or thymic carcinoma demonstrated prolonged TTF on mTOR inhibitor-based therapy as compared to prior conventional treatment." (PMID 23765114, 2013).
tumor syndrome (6 papers, 2013 to 2024). "The mammalian target of rapamycin (mTOR) pathway was initially studied in NETs as a part of familial tumor syndromes known to have genetic mutations in genes upstream of the mTOR complexes." (PMID 29255447, 2017). "TSC1 and TSC2 are the tumor-suppressor genes mutated in the tumor syndrome TSC (tuberous sclerosis complex) and their gene products form a complex (TSC1–TSC2) that integrates signals upstream of mTOR signaling pathway through its GAP activity towards the small G-protein Rheb." (PMID 23977024, 2013).
viral hepatitis (6 papers, 2014 to 2021). An acute or chronic inflammation of the liver parenchyma caused by viruses. "At the molecular level, mammalian target of rapamycin (mTOR) pathway was found to be associated with HCC development including chronic viral hepatitis." (PMID 24804240, 2014). "The role of the mTOR pathway in chronic viral hepatitis concerns the regulation of cellular homeostasis." (PMID 32070029, 2020). "mTOR was activated in precancerous cirrhotic tissues in addition to chronic viral hepatitis tissues." (PMID 24804240, 2014). "Together, this study has revealed for the first time a hepatoprotective role of metformin in acute viral hepatitis via mechanisms that include restraining excessive T cell infiltration and activation in the liver, inhibiting the mTOR signaling via a TSC1-dependent manner in T cells." (PMID 33968030, 2021). "Mammalian target of rapamycin (mTOR) pathway is activated in viral hepatitis and HCC." (PMID 24804240, 2014).
acute GVHD (5 papers, 2016 to 2022). "Given that a randomized trial of 74 patients showed a significant reduction in acute GVHD with tacrolimus and sirolimus, a mTOR inhibitor, compared with tacrolimus and methotrexate, further studies will analyze the effect of including MSCs with tacrolimus and sirolimus." (PMID 26933811, 2016). "The responses of AKT (Thr308), mTOR (Ser2448) and STAT3 (Ser727) were generally stronger for patients with previous acute GVHD; i.e., usually highly significant responses for all three phosphosites and all three cell subsets." (PMID 35566660, 2022). "To conclude, circulating T cells as well as CD3− cells derived from allotransplant recipients with previous acute GVHD showed generally stronger PMA phosphoresponses for AKT (Thr308), mTOR (Ser2448) and STAT3 (Ser727), than T cells from patients without previous GVHD." (PMID 35566660, 2022). "STAT3 (Tyr705) responses were stronger for patients with previous acute GVHD; CD3+CD4+ cells from GVHD patients showed an additional STAT3 (Ser727) response, whereas patients without acute GVHD showed additional mTOR (Ser2448) responses." (PMID 35566660, 2022). "Thus, post-transplant T cells derived from patients with and without previous acute GVHD show similar STAT3 (Tyr727) phosphoresponses to IL-6, whereas STAT3 (Ser727) and mTOR (Ser2448) responses differ between the two patient subsets." (PMID 35566660, 2022). "Thus, activated CD3+CD8+ T cells showed no major differences in IL-6 responsiveness when comparing patients with and without previous acute GVHD; this is in contrast to the CD3+CD4+ T cell subset that differed in STAT (Ser727) and mTOR (Ser2448) responses between the two patient subsets." (PMID 35566660, 2022).
amnesia (5 papers, 2017 to 2025). Pathologic partial or complete loss of the ability to recall past experiences ( AMNESIA, RETROGRADE) or to form new memories ( AMNESIA, ANTEROGRADE). "However, high concentrations of rapamycin completely inhibit mTOR, affect long-term memory facilitation and consolidation, and cause amnesia." (PMID 28143498, 2017).
amyloid (5 papers, 2020 to 2025). "However, sustained overactivation of PI3-K/Akt/mTOR signaling has been documented in AD brains and is associated with amyloid and tau pathogenesis." (PMID 41331787, 2025). "It will support the potential efficacy of mTOR inhibitor on preventing organ damage and secondary amyloidosis in iMCD with inadequate TCZ response and on significantly improving quality of life and vital prognosis." (PMID 32791665, 2020).
anal carcinoma (5 papers, 2013 to 2022). "These regimens include rapamycin- a putative mTOR inhibitors that could have greater success in treating human anal cancer, and could reduce instances of morbidity associated with the standards of treatment that are currently available." (PMID 24124460, 2013). "It has been previously shown that the topical administration of BEZ235, a dual PI3K/mTOR pathway inhibitor, prevents anal carcinogenesis in a mouse model of HPV-associated anal cancer." (PMID 36683775, 2022). "In this study, we compare the topical versus oral (systemic) administration of LY3023414, a dual PI3K/mTOR inhibitor, in order to slow the progression of anal dysplasia to anal cancer." (PMID 36683775, 2022). "Phospho-S6 (pS6), the active form of the effector S6 for mTOR signaling, is upregulated in HPV-associated anal cancers." (PMID 32398315, 2020). "The preclinical mouse models also indicated that there was activation of mTOR in DMBA-induced anal cancers using HPV E6 and E7 transgenic mice." (PMID 24124460, 2013). "A study from the hospital of Wisconsin University has shown that the activation of mTOR was frequently detected in human anal cancers." (PMID 24124460, 2013). "We have also demonstrated important role of the Akt/mTOR pathway in anal cancer progression, and its inhibition by rapamycin treatment results in delayed cancer progression indicating therapeutic potential of rapamycin in treating anal cancer." (PMID 24124460, 2013). "The PI3K and mTOR pathways are dysregulated in many cancers, including anal cancer." (PMID 36683775, 2022). "In this study, we compare a topical versus systemic (oral) administration of LY3023414, a dual PI3K/mTOR inhibitor, to prevent anal carcinogenesis in a Human Papillomavirus (HPV) mouse model of anal cancer." (PMID 36683775, 2022). "Here we report that Tgfbr1/Pten double conditional knockout mice spontaneously develop anal cancer in a short period of time with activation of the Akt/mTOR pathway and without carcinogen induction." (PMID 24124460, 2013).
anaplastic large cell lymphoma (5 papers, 2013 to 2026). Anaplastic large cell lymphoma (ALCL) is a rare and aggressive peripheral T-cell non-Hodgkin lymphoma, belonging to the group of CD30-positive lymphoproliferative disorders, which affects lymph nodes and extranodal sites. "Inhibition of mTOR with rapamycin- or mTOR-specific small interfering RNA downregulated Bcl-2 and Mcl-1 in anaplastic large-cell lymphoma cells." (PMID 24647338, 2014). "Activation of mTOR contributes to tumor cell survival in ALK (anaplastic lymphoma kinase)-positive ALCL (anaplastic large cell lymphoma), mantle cell lymphoma, childhood B-precursor ALL, T-ALL, and AML." (PMID 23431463, 2013).
anxiety disorder (5 papers, 2020 to 2024). A category of psychiatric disorders which are characterized by anxious feelings or fear often accompanied by physical symptoms associated with anxiety. "Ketamine dose-dependently activated mTOR, ERK, and AKT; the mTOR antagonist rapamycin blocked the antidepressant effects of ketamine, indicating functional significance of the mTOR pathway in mood and anxiety disorders." (PMID 32998470, 2020). "Specifically, several biological processes, pathways, and diseases, including anxiety disorder (umls: C0003469), Alternative mRNA splicing (GO: 0000380), circadian rhythm (GO: 0007623), and mTOR signaling pathway (R-HSA-165159) are closely related to ASD." (PMID 33173536, 2020).
benign prostatic hyperplasia (5 papers, 2012 to 2023). A non-cancerous nodular enlargement of the prostate gland. "TRAF6 was confirmed to regulate stromal cell proliferation through the Akt/mTOR signaling pathway in prostatic hyperplasia." (PMID 32724313, 2020). "Some immunohistochemistry studies had shown the elevated expressions of phospho-Akt, phospho-mTOR were observed in PCa tissues compared with benign prostatic hyperplasia(BPH) and high-grade prostatic intraepithelial neoplasia(HGPIN) tissues." (PMID 22815832, 2012).